INS (insulin)
Diseases named in the same sentence as INS in open-access papers (continued):
Sharing a sentence is not in itself a finding about the gene and the disease.
cerebral infarction (15 papers, 2014 to 2026). An ischemic condition of the brain, producing a persistent focal neurological deficit in the area of distribution of the cerebral arteries. "Univariate MR results indicated that the use of blood pressure medication, insulin, and cholesterol‐lowering medication was significantly associated with the occurrence of cerebral infarction (all p < 0.05)." (PMID 39710996, 2024). "Using Mendelian randomization analysis, we found that the abuse of blood pressure medication and insulin were potential risk factors for cerebral infarction." (PMID 39710996, 2024). "This study suggests that the misuse of blood pressure medications and insulin is a risk factor for the occurrence and progression of cerebral infarction." (PMID 39710996, 2024). "The results further confirmed a positive causal relationship between blood pressure medications, insulin, and cerebral infarction." (PMID 39710996, 2024). "In conclusion, our results showed a positive association between blood pressure medication and insulin with cerebral infarction." (PMID 39710996, 2024). "The results of the analysis offer genetic support for a causal association between blood pressure medication, insulin, and cerebral infarction." (PMID 39710996, 2024). "Multivariable MR (MVMR) models were developed based on univariate MR analysis to investigate the causal association between cholesterol‐lowering medication, blood pressure medication, insulin, and the risk of cerebral infarction." (PMID 39710996, 2024). "Furthermore, the MVMR analysis, which builds upon univariate MR, only identified significant causal associations between blood pressure medication, insulin, and cerebral infarction (p < 0.05)." (PMID 39710996, 2024). "This study provides substantial evidence that the misuse of blood pressure medications and insulin may be a potential risk factor for cerebral infarction." (PMID 39710996, 2024). "The findings from MR analysis indicated that the misuse of blood pressure medication and insulin could be a potential risk factor in the onset and progression of cerebral infarction." (PMID 39710996, 2024). "This association could explain cerebral infarction induced or exacerbated by excessive insulin use, consistent with the results of our comprehensive MR analysis." (PMID 39710996, 2024). "After integrating the findings from both univariate and MVMR and controlling for confounding variables to the greatest extent possible, the available evidence supports only a potential causal relationship between blood pressure medication, insulin, and cerebral infarction." (PMID 39710996, 2024). "However, insulin treatment was linked to a marked increase in cerebral infarct size in patients with complete intracranial vascular occlusion." (PMID 37025208, 2023). "In this study, we showed in the subset of individuals with ex vivo stimulation data, that a greater phosphorylation of a downstream molecular marker of insulin signaling, pT308AKT1 following ex vivo stimulation of brain tissue with insulin, was associated with more brain infarcts." (PMID 33858515, 2021). "Thus, the current result of an association of greater pT308AKT1 with more brain infarcts adds to the literature in the field of insulin signaling in the aging brain." (PMID 33858515, 2021). "Additionally, the relationship between insulin, exogenous hormones, and the risk of cerebral infarction remains unclear." (PMID 39710996, 2024). "There was a significant positive causal relationship between blood pressure medication (OR: 1.009710 [1.0031017, 1.016361], p = 0.003921084), insulin (OR: 1.051087 [1.0016765, 1.102935], p = 0.042541027), and cerebral infarction." (PMID 39710996, 2024). "To investigate the association between the misuse of common medications—such as Cholesterol‐lowering medication, blood pressure medications, insulin, and exogenous hormones—and cerebral infarction, we conducted a comprehensive MR analysis." (PMID 39710996, 2024).
cerebral infarction (continued). "This study investigated the effects of cholesterol‐lowering medication, blood pressure medication, insulin, and exogenous hormones on cerebral infarction." (PMID 39710996, 2024). "By analyzing the available data, a significant positive causal relationship between the misuse of blood pressure medication, insulin, and cerebral infarction was determined." (PMID 39710996, 2024). "Excessive use of blood pressure medication and insulin can induce and aggravate cerebral infarction." (PMID 39710996, 2024). "Our univariate MR findings indicated a positive causal relationship between blood pressure medications, cholesterol‐lowering medication, insulin, and cerebral infarction." (PMID 39710996, 2024). "More recently, the INSULINFARCT trial showed that the brain infarcts intensively treated with insulin were larger than the infarcts treated with the usual dose of subcutaneous insulin." (PMID 36038896, 2022). "In the subgroup of 79 subjects with ex vivo insulin stimulation data available, greater AKT phosphorylation (pT308AKT1) was associated with a higher number of brain infarcts." (PMID 33858515, 2021). "To better understand plausible mechanisms linking insulin resistance to brain infarcts, we next examined the relation of insulin signaling and related measures to three common cerebral vessel pathologies in aging." (PMID 33858515, 2021). "Pretreatment with insulin alleviated—but glucose augmented—postischemic brain infarction, caspase 3 activity, and TNF-α protein." (PMID 32492962, 2020). "It has a possibility that CRBN directly regulates insulin-dependent signaling pathway in the molecular mechanism of thalidomide’s neuroprotective effect on cerebral infarction." (PMID 29410497, 2018). "In clinical practice, personalized approaches and appropriate utilization of blood pressure medication and insulin could serve as effective strategies for the prevention and management of cerebral infarction." (PMID 39710996, 2024). "Insulin may be reducing the size of brain infarcts through the direct interaction of IGF-1 with brain tissue." (PMID 37025208, 2023). "Plasma glucose and insulin levels in diabetic rats were 508 ± 43 mg/dl and 0.61 ± 0.10 μg/l compared with values of 194 ± 7 mg/dl and 3.07 ± 0.36 μg/l in age-matched non-diabetic controls, respectively (P < 0.001 and P < 0.05) 24 hr after cerebral infarction." (PMID 25223305, 2014). "In T2DM patients, insufficient insulin secretion or reduced insulin sensitivity leads to chronic hyperglycemia, which increases blood viscosity, promotes thrombus formation, and may result in vascular blockage, ultimately inducing cerebral infarction." (PMID 40313488, 2025). "Therefore, intensive insulin treatment is not recommended in the hyperacute phase of cerebral infarction." (PMID 37025208, 2023).
cervical carcinoma (15 papers, 2007 to 2025). A carcinoma arising from either the exocervical squamous epithelium or the endocervical glandular epithelium. "The HeLacell line used in our GLUT4 translocation experiment is derived fromhuman cervical carcinoma cells but is also insulin responsive." (PMID 40392982, 2025). "Altered insulin signaling pathways involved in promoting cellular glucose uptake and proliferation have also been frequently detected in cervical cancer." (PMID 38664791, 2024). "This suggests that the insulin signaling cascade is involved in the growth and proliferation of cervical cancer cells." (PMID 36975518, 2023). "The relationship between the expression levels of IRS-1 and IRS-2 and the activation of insulin signaling pathways has been poorly studied in cervical cancer cells." (PMID 36975518, 2023). "We study the participation of the insulin substrates IRS-1 and IRS-2 in the insulin signaling pathway in response to insulin and their involvement in the proliferation and migration of the cervical cancer cell line." (PMID 36975518, 2023). "L-arginine potentiates insulin secretion also in other cell lines such as fibroblasts and cervical carcinoma cells incubated with an adenovirus containing the human insulin cDNA." (PMID 17941991, 2007). "Notably, there is very little information in the literature related to the role of the insulin signaling pathway in the carcinogenesis of cervical cancer." (PMID 36975518, 2023). "It has been reported that progesterone upregulates IRS-2 expression, altering the levels of IRS-1 and IRS-2 in HeLa cells expressing progesterone receptors; however, very little is known about the role of the insulin signaling pathway in cell proliferation and migration in cervical cancer." (PMID 36975518, 2023). "We seek to address this void by examining insulin signal transduction in the cervical cancer cell line HeLa, which has not previously been examined." (PMID 36975518, 2023). "Interestingly, Mkrn1 functions as a positive-feedback regulator of the PI3K/AKT signals in cervical cancer progression because it is stabilized by AKT-mediated phosphorylation and it destabilizes Pten, which leads to further activation of the insulin signaling pathway." (PMID 31009498, 2019). "To determine whether the stimulatory effect of L-arginine on insulin secretion is specific to liver cells or not, we incubated the following cell lines with the human insulin adenovirus: HepG2 (human liver), NIH3T3 (mouse fibroblast) and HeLa (human cervical carcinoma)." (PMID 17941991, 2007).
Hyperbilirubinemia (15 papers, 2012 to 2025). An increased amount of bilirubin in the blood. "Neonatal jaundice/hyperbilirubinemia was reported as an outcome between glyburide and insulin by 5 studies which included 1618 GDM patients." (PMID 31781670, 2019). "Neonatal jaundice/hyperbilirubinemia was included as an outcome between metformin and insulin by 13 studies which involved 2378 GDM patients." (PMID 31781670, 2019). "However, there was no significant statistical difference between the metformin and insulin groups in terms of neonatal jaundice/hyperbilirubinemia (RR, 1.07; 95% CI, 0.94 to 1.23; P = 0.31)." (PMID 31781670, 2019). "However, there was no significant statistical difference between the glyburide and insulin groups in terms of neonatal jaundice/hyperbilirubinemia (RR, 1.09; 95% CI, 0.84 to 1.41; P = 0.52)." (PMID 31781670, 2019). "Their analysis included fewer interventions than did in our analysis; have not included the intervention of metformin plus insulin and the outcomes of RDS and hyperbilirubinemia; and have not presented the contribution plot and cumulative probability plot." (PMID 28930827, 2017).
Hypernatremia (15 papers, 2013 to 2026). An abnormally increased sodium concentration in the blood. "In this cohort, the following variables are associated with ICU and hospital mortality: age, APACHE IV PM, maximal SOFA score, hypernatremia, percentage BG measurements < 4.4 mmol/L and the amount of intravenous insulin increased the risk of mortality." (PMID 30742240, 2019). "Hypernatremia can cause neurological manifestations and is associated with multiple systemic adverse effects, including increased insulin resistance, decreased lactate clearance, impaired left-ventricular contractility, and prolonged mechanical ventilation days." (PMID 36140385, 2022). "Hypernatremia has been shown to be associated wit peripheral insulin resistance, impaired hepatic lactate clearance, decreased left ventricular contractility or various neuromuscular manifestations ranging from muscle weakness to delayed weaning from mechanical ventilation." (PMID 23336363, 2013). "Despite fluid resuscitation and insulin therapy, refractory hypernatremia persisted, leading to a diagnosis of central diabetes insipidus (CDI)." (PMID 41211065, 2025). "In contrast, pathological factors such as oxidative stress and hypernatremia can resist this action of insulin and thus become pro-diabetic." (PMID 36077440, 2022). "Patient was given initial bolus of isotonic saline and continued on half isotonic saline for correction of hypernatremia along with insulin infusion therapy." (PMID 30112226, 2018). "The relationship between hypernatremia and adverse prognosis could be due to decreased left ventricular contractility and/or increased peripheral insulin resistance." (PMID 36312256, 2022). "As a result of high insulin sensitivity at that stage and to avoid rapid drop in blood sugar with standardized insulin treatment and development of hypernatremia, the patient was managed on the intensive care unit with meticulous rehydration and a gradual, slow reduction in plasma glucose." (PMID 31752481, 2020). "The following variables are independently associated with ICU and hospital mortality in multiple regression analysis: age, APACHE IV PM, maximal SOFA score, hypernatremia (average sodium > 145 mmol/L), percentage BG measurements < 4.4 mmol/L and the amount of intravenous insulin and fluid balance." (PMID 30742240, 2019). "Nevertheless, it is important not to prolong hypernatremia duration which induces cerebral suffering and the risk of neurological sequels, decreases cardiac contractility, increases peripheral insulin resistance and impairs hepatic neoglucogenesis." (PMID 24559470, 2014).
kidney (15 papers, 2008 to 2026). "In kidney transplant recipients undergoing an oral glucose tolerance test during one-year surveillance follow-up we estimated insulin sensitivity with the Matsuda index, a modified Stumvoll index, and HOMA-2IR." (PMID 39911868, 2025). "It primarily mitigates kidney damage by enhancing insulin sensitivity, bolstering lipid metabolism, alleviating inflammation and oxidative stress within the kidneys, among other mechanisms." (PMID 40931579, 2025). "Studies have confirmed that inflammation and immune factors (IgE, complement C4, complement C3, CRP, ASO, and RF) and hormone elements (Osteoc, FSH, testosterone, and insulin) are significantly related to the occurrence of prostatitis." (PMID 36071874, 2022). "Several lines of experimental evidence have pointed to the role of insulin in the enhancement of prostate carcinogenesis, particularly in advanced PCa." (PMID 33692752, 2021). "Synthesis from glutamate requires ammonia as the nitrogen donor and therefore, the higher metabolic rate through this pathway in AMPD1 KO mice would help both detoxify ammonia and reduce urea production to ameliorate kidney dysfunction and improve insulin sensitivity." (PMID 36994079, 2023). "Meanwhile, the low-salt diet improved insulin sensitivity and prevented kidney damage." (PMID 34836175, 2021). "Finally, metabolic abnormalities can lead to insulin (but also to IGF1 and E2)-mediated prostate inflammation and hyperplasia." (PMID 33692752, 2021). "Therefore, reduced glucose-induced insulin secretion and reduced glucagon suppression may contribute to PTDM in kidney transplant recipients." (PMID 38397919, 2024). "All groups remained insulin sensitive, but 16- to 18-week-old male RT-SAKO mice became glucose intolerant, without developing kidney inflammation or fibrosis." (PMID 38280449, 2024).
placental insufficiency (15 papers, 2010 to 2025). Failure of the placenta to deliver an adequate supply of nutrients and oxygen to the fetus. "Fetal adaptations to placental insufficiency alter postnatal metabolic homeostasis in skeletal muscle by reducing glucose oxidation rates, impairing insulin action, and lowering the proportion of oxidative fibers." (PMID 22900186, 2012). "High adrenaline concentrations are particularly potent inhibitors of the secretion and action of growth factors, and fetal sheep data show that reduced circulating levels of insulin, IGFs, and other growth-stimulating hormones are concomitant with placental insufficiency." (PMID 31608163, 2019). "Furthermore, when we prevented the capacity for rises in catecholamines by surgically ablating the adrenal medulla in fetal sheep, the subsequent impact of both hypoxemia and placental insufficiency on insulin secretion were diminished markedly." (PMID 31608163, 2019). "However, placental insufficiency in fetal sheep reduces plasma insulin by 78% and skeletal muscle Akt2 content by 40%." (PMID 22900186, 2012). "However, in contrast to our rodent model of placental insufficiency, insulin secretion is impaired in young adult male but not female sheep exposed to placental restriction whereas insulin secretion in our rodent model is blunted only in female IUGR at 12 months of age." (PMID 29145418, 2017). "In rodent models of placental insufficiency, young adolescent male offspring show altered GLUT4 transport in conjunction with an increased phosphorylation of IRS-1, which is known to blunt the physiological response to insulin by reducing the coupling efficiency of the insulin receptor and IRS-1." (PMID 25685986, 2015).
Wolfram syndrome (15 papers, 2010 to 2025). Wolfram syndrome (WS) also known as DIDMOAD, is a neurodegenerative disorder characterized by type I diabetes mellitus (DM), diabetes insipidus (DI), sensorineural deafness (D), bilateral optical atrophy (OA) and neurological signs. "Wolfram syndrome is a rare genetic disorder characterized by juvenile-onset diabetes mellitus with impaired insulin secretion, hearing loss, central diabetes insipidus, optic nerve atrophy, and neurodegeneration." (PMID 28208663, 2017). "One of the UPR components is WFS1 (Wolfram syndrome 1), which plays important roles in ER homeostasis and pancreatic islets glucose-stimulated insulin secretion (GSIS)." (PMID 36725880, 2023). "According to previous research, WFS1 (Wolfram syndrome 1) is involved in the synthesis and release of insulin, as well as the preservation of the pancreatic β cell mass." (PMID 36725880, 2023). "We also identified that patient SC-islets demonstrated genotype-phenotype relationships that correlated with clinical observations, and a combination treatment with 4-PBA and TUDCA improved insulin secretion in this cellular model of Wolfram syndrome." (PMID 36134655, 2022). "It has been shown that 4-PBA can improve insulin synthesis in iPSC-derived β cells from patients with typical Wolfram syndrome." (PMID 36134655, 2022). "A 16 week liraglutide administration in an adult with Wolfram syndrome transiently (4 weeks) improved glucose tolerance, while in another individual with an autosomal dominant WFS1 mutation insulin therapy could be discontinued with GLP-1 analogue treatment." (PMID 36995380, 2023). "Moreover, exenatide administration in one Wolfram syndrome 2 patient resulted in a 70% reduction in daily insulin requirements, improved glycemic control, and 7-fold increase in maximal insulin secretion." (PMID 34992533, 2021). "However, transplanting insulin-producing cells established from iPS cells of patients with Wolfram syndrome to immunodeficient mice, glucose intraperitoneal administrations revealed significantly lower insulin responses in Wolfram β-cells." (PMID 28208663, 2017). "A recent study showed that in human pluripotent stem cells, derived insulin-producing β cells (sc-β cells) with or without gene collection of the pathogenic variant of Wolfram Syndrome (WS) revealed a 1.5–2-fold TXNIP gene induction by high glucose stimulation." (PMID 32824669, 2020). "Notably a recent study looked directly at acute effects of subcutanous exendin-4 treatment in wild-type mice (as well as insulin-deficient Wolfram syndrom mice) and found no decrement of circulating glucagon levels." (PMID 28702245, 2016). "On the other hand, in dulaglutide-treated mice gliclazide and KCl, but not high glucose, stimulated insulin secretion, showing that GLP-1R agonists increase at least in part the function of beta cells from individuals affected by Wolfram syndrome." (PMID 36995380, 2023).